NRP1 (neuropilin 1)
Diseases named in the same sentence as NRP1 in open-access papers (continued):
Sharing a sentence is not in itself a finding about the gene and the disease.
cancer (continued). "Research has shown that NRP1 plays a significant role in the development and progression of various cancer types and also more recently in the infectivity of severe acute respiratory syndrome coronavirus 2 (SARS-CoV-2)." (PMID 37513474, 2023). "This combination along with the anti-cancer drug curcumin formed self-assembled spherical nanocapsules, which specifically targeted neuropilin-1-rich cancer cells." (PMID 37998127, 2023). "As a result, we revealed that CD inhibits NRP1 expressed in cancer cells and prevents viral syncytial formation in 293T-hACE2 cells, implying the therapeutic potential for both anti-cancer and anti-viruses, including anti-SARS-CoV-2." (PMID 38138098, 2023). "Collectively, our research highlights an efficient personalized therapy via NRP1/EGFR signaling of malignant tumors." (PMID 37891570, 2023). "Based on these results and published studies employing this NRP1 antagonist in cancer cells, we selected 15 μM EG for the following experiments." (PMID 36376373, 2023). "In cancer, other groups have shown that Nrp-1 expression on CD8+ T cells is induced during disease progression." (PMID 38019895, 2023). "AhR and Nrp1 are both expressed in several cell types including neurons, keratinocytes, and several cancer cell lines." (PMID 38035105, 2023). "In their naïve state, CD8+ T cells display low levels of Nrp-1 expression, which are significantly elevated during persistent gamma-herpes virus infection, autoimmune diseases and cancer." (PMID 38019895, 2023). "The expressional levels for ACE2 and NRP1 mRNA occupy first and second position across all cancers analysed for CCRCC and PRCC, whereas TMPRSS2 was more modestly expressed." (PMID 36595529, 2023). "In nearly all cancers, NRP1 expression was positively correlated with the expression of most immune checkpoint genes." (PMID 37190154, 2023). "As expected, NRPs showed significantly higher sensitivity and specificity for the diagnosis of various cancers, especially PAAD, and NRP1 also showed a high diagnostic value in CHOL." (PMID 37190154, 2023). "Most of these CAF-related genes are associated with tumorigenesis and cancer progression, including GLT8D1, GPX3, NRP1, PPP1R26, SERPINE1, and TMSB15A." (PMID 36717783, 2023). "Although most of the work performed on NRP1 inhibition in cancer to date remains at the preclinical stage, clinical research initiatives have emerged." (PMID 37894289, 2023). "NRPs, especially NRP1, are attractive biomarkers and therapeutic targets for cancers, particularly PAAD." (PMID 37190154, 2023). "The introduction of iRGD not only enhanced the water solubility of compound 76 but also inhibited cancer cell metastasis by targeting αv integrins and neuropilin-1 overexpressed on the surface of several kinds of cancer cells." (PMID 37446591, 2023). "Before being a common mediator of SARS-CoV-2 virus infection, NRP1 has been a regular visitor in cancer research, and it has been proved to be related to the immune system." (PMID 36875081, 2023). "In fact, their associations (SCARB1 most in all investigated 33 cancers, followed by NRP1 in 31 cancers, TMPRSS2 in 27 cancers, AXL in 25 cancers and ACE2 in 13 cancers) appeared in more cancer types than those of CNVs with the same trends among the five STGs." (PMID 36875081, 2023). "Our study found that CD inhibits the NRP1 expression of both protein and mRNA levels in a dosage-dependent manner in various cancer cell lines, implying the therapeutic potential for anti-SARS-CoV-2 and anti-cancers." (PMID 38138098, 2023). "It is worth noting that NRP1 is expressed not only on cancer cells but also on immune cells such as regulatory T cells." (PMID 37371647, 2023). "Targeting of Sema3A or NRP1 can be an alternative therapeutic approach to inhibit oncogenic TGF-β signaling in cancer." (PMID 37788099, 2023).
cancer (continued). "Patient-derived cancer cells were sorted using anti-NRP1 or anti-IGF1R antibodies and cultured in floating spheroid-forming conditions for CSC enrichment (left)." (PMID 37966117, 2023). "The GSE10645 PCa cohort results demonstrated that PCa patients in the high NRP1 expression group indicated shorter overall survival (OS) rate and cancer-specific survival (CSS) rate than those in the low NRP1 expression group (P < 0.0001; P < 0.0001)." (PMID 36841806, 2023). "Here, we confirmed that the expression of NRPs, especially NRP1, was positively correlated with most of the immune checkpoint expression in nearly all cancers, including PAAD." (PMID 37190154, 2023). "Considering the double-edged role of autophagy in cancer and the interesting role of NRP1 in the lenvatinib-derived inhibition of HCC cell proliferation and migration, we decided to assess the relationship between them." (PMID 36376373, 2023). "The same phenotype has been observed in cancer: Nrp-1 expression on CD8+ T cells was accompanied by elevated expression of CD44, CD69 and CD25, but also by several co-inhibitory molecules such as PD-1, CTLA-4, Lag-3 and Tim-3." (PMID 38019895, 2023). "GAIP-interacting protein C terminus (GIPC1) is a scaffold protein that also interacts with the NRP1 cytoplasmic region; moreover, NRP1 induces cancer cell proliferation by forming a complex that contains GIPC1." (PMID 37108554, 2023). "NRP1 plays multiple roles in axon guidance, angiogenesis, immunosuppression, cancer progression, and other physiological or pathological processes." (PMID 36446758, 2022). "In cancer cells, NRP1 mediates ligand-induced EGFR clustering and endocytosis, leading to intracellular activation of the AKT signaling cascade." (PMID 35347234, 2022). "In conclusion, we identified NRP1 as a potential biomarker in predicting susceptibility to SARS-CoV-2 infection among healthy people and cancer patients." (PMID 36338984, 2022). "The effects of Nrp1 inhibition on CD8+ and Treg cells, or the possibility of using Nrp1 expression as a cancer biomarker make Nrp1 a promising candidate molecule for study." (PMID 36203599, 2022). "Although the NRP-1 importance in cancer has been well-known, the precise role of NRP-2 in oncogenesis has just lately been investigated." (PMID 35052853, 2022). "Neuropilin-1 (NRP1) is a cell surface receptor which is important in cancer progression, angiogenesis, immune function and axonal guidance." (PMID 36231049, 2022). "The overexpressed of NRP1 in various cancers, including MB, has been reported to has been correlated with poor prognosis with upregulation of cell proliferation or migration." (PMID 36457009, 2022). "Increasing evidence on the involvement of NRP1 in cancer and immune processes has triggered research interests worldwide." (PMID 35281516, 2022). "Based on these we also investigated the relationship between NRP1 expression and chemokine/chemokine-receptor at a pan-cancer level in TISIDB." (PMID 36338984, 2022). "Cancer patients with high expression level of NRP1 were presumed to be vulnerable to the infection of SARS-CoV-2, and they were more likely to experience cytokine storm." (PMID 36338984, 2022). "Neuropilin-1 (NRP1) is a transmembrane protein overexpressed in advanced human tumors, typically exhibiting growth-promoting functions in cancer cells." (PMID 35993027, 2022). "Neuropilin-1 (NRP1) is a transmembrane protein involved in numerous cellular functions which has had increasing interest from cancer researchers." (PMID 35884516, 2022). "Studies have shown that NRP1 is upregulated in Tregs to regulate their stability and function of immune system in cancer patients." (PMID 36406134, 2022). "The synthesized radioconjugates were tested for their possible use as theranostic-like radiopharmaceuticals for the imaging and therapy of cancers that overexpress NRP-1." (PMID 35056995, 2022).
cancer (continued). "In most cancer types expression of NRP1 was positively related with expression of immunoinhibitory markers and chemokines/chemokine-receptors." (PMID 36338984, 2022). "The designed platform was noted to bind to NRP1 in cancer cells, disrupt its complex formation with PlexA1, downstream Akt survival signaling, and inhibit angiogenesis and cell migration." (PMID 35563645, 2022). "Data showed that the many immune checkpoints positively correlate with CD93 expression in many cancers, particularly NRP1, LAIR1, VSIR, and CD86." (PMID 36389798, 2022). "VEGF/NRP1 are promoting angiogenesis and pro-tumorigenic signaling in both endothelial and cancer cells." (PMID 35252204, 2022). "Among the ligands of NRP1, VEGF-A is the best-known binding partner that mediates the pro-angiogenic and pro-invasive role of NRP1 in cancer through a co-interaction with NRP1/VEGFR2." (PMID 35884516, 2022). "Along with survival outcomes, NRP1 has been demonstrated to be involved in therapeutic responsiveness in cancer patients." (PMID 35884516, 2022). "Neuropilin-1 (NRP1) is a transmembrane protein which has had recently increased interest from cancer researchers." (PMID 35884516, 2022). "Nrp‐1 is a key factor in controlling cerebral angiogenesis, cancer generation and recurrence, and fibrosis of the liver by regulating the TGF‐β1 pathway." (PMID 34758202, 2022). "In cancer cells, the extracellular domain of NRP1 can interact with EGFR and promote the EGFR signaling cascade elicited upon EGF stimulation." (PMID 35347234, 2022). "Our findings complement the pro-tumorigenic effects of NRP-1 in cancer cells, such as modulating EMT, evasion of contact inhibition or promoting angiogenesis." (PMID 36338759, 2022). "Our research identified NRP1 as a valuable marker in predicting vulnerability to SARS-CoV-2 infection among normal people, however, the susceptibility to SARS-CoV-2 in cancer patients merits further investigation." (PMID 36338984, 2022). "This work unveiled the role of the Nrp1:VEGF axis in a stem cell niche where therapeutic intervention against Nrp1 holds the potential to reduce cancer stem cell stemness." (PMID 36203599, 2022). "Cancer patients were divided into high- and low-NRP1 group according to median NRP1 expression level." (PMID 36338984, 2022). "Neuropilin-1 plasma level was higher in patients with type 2 EC (G3) compared to patients with lower grade cancer or controls." (PMID 36505829, 2022). "qRT-PCR revealed upregulation of VEGF-A, Nrp1, and Hif1α in the epithelial cancer stem cell-derived tumors." (PMID 36203599, 2022). "The puzzling results that we obtained in the present and in our previous study, highlight the relative importance of NRP1 or NRP2 signaling depending on the cancer type." (PMID 33461580, 2021). "Associations of NRP2, NRP1 and several NRP ligands (i.e., PDGFC and PDGFD) that have been implicated in cancer progression were analyzed." (PMID 33918816, 2021). "These series of lead compounds represent a first step in development of small molecule inhibitors for the SARS-CoV-2 S–NRP1 interaction and for certain types of cancer where NRP1 plays a disease-promoting role." (PMID 34961486, 2021). "While the NRP1 staining in normal bladder tissues was generally not detected, a high proportion of the BC tissues displayed high (1/12), moderate (4/12) or low (6/12) NRP1 staining, which was typically located in the cytoplasm and membrane of cancer cells." (PMID 34249735, 2021). "The overexpression of NRP1 is reported in several types of cancers such as colon, stomach, lung, osteosarcoma, breast, astrocytoma, glioma, melanoma, and is considered to be a negative prognostic marker for the disease outcome." (PMID 34961486, 2021). "Tobacco mosaic virus (TMV) coat protein (CP) is one of the reported nanocarriers for a hydrophobic and insoluble peptide that targets the cancer cell receptor Neuropilin-1 (NRP1)." (PMID 34451955, 2021).
cancer (continued). "NRP-1 is a transmembrane glycoprotein overexpressed in multiple cancers (including GBM) and in angiogenic endothelial cells in tumour vasculature." (PMID 34868634, 2021). "Among these significantly activated pathways, the molecular mechanisms of cancer pathway was chosen to examine the potential role of NRP1 in BC." (PMID 34249735, 2021). "Strikingly, the results suggested that LATS2 expression and NRP1 expression were positively correlated in all 33 cancers." (PMID 34699318, 2021). "Specifically, downregulation of NRP1 contributes to BC progression, which is associated with activation of MAPK signaling and molecular mechanisms involved in cancer pathways." (PMID 34249735, 2021). "Several miRNAs have been demonstrated to regulate NRP-1 expression and participate in the progression of various types of cancer." (PMID 33912463, 2021). "The expression of NRP1 can be detected in a variety of malignant cells and urinary tract cancer cells in Cancer Cell Line Encyclopedia (CCLE) database." (PMID 34249735, 2021). "Hybrid ligand 10, a silylated analogue of the antiangiogenic peptide H-ATWLPPR-OH, a neuropilin-1 receptor (NRP1) antagonist involved in cancer, was selected as the second ligand." (PMID 33445812, 2021). "NRP-1, involved in cell survival and proliferation, seems to favor an undifferentiated phenotype in cancer cells and its overexpression has been reported to be correlated with a poor prognosis in both GBM and MB." (PMID 34638864, 2021). "In particular, we detail the role of NRP1 in cancer stem cells and immune system cells during tumorigenesis." (PMID 34277411, 2021). "Neuropilin-1 plasma levels were significantly higher in patients with type 2 EC (grade 3) compared to patients with lower grade cancer or controls." (PMID 33671851, 2021). "NRP-1 is involved in the progression of various cancer types by co-activating multiple cognate receptor tyrosine kinase signaling pathways." (PMID 33912463, 2021). "NRP1 expression correlates with radio-resistance, and NRP1 antagonism in human cancer cells inhibits migration and enhances chemosensitivity." (PMID 34503301, 2021). "It is assumed that NRP-1 promotes cancer by binding to molecules involved in angiogenesis and epithelial-to-mesenchymal Transition (EMT)." (PMID 33884469, 2021). "Taken together, these findings provide novel insights into the molecular mechanisms by which NRP1 drives the pathogenesis and progression of cancer." (PMID 34249735, 2021). "NRP1 silencing was related to many cancer-related functions, which is consistent with the results of cell function experiments." (PMID 34249735, 2021). "Recently, ELISA-based quantification of soluble NRP-1 (sNRP-1) has become available, but little is known about the prognostic value of sNRP-1 in malignancies." (PMID 33884469, 2021). "In murine cancer models, deletion of neuropilin 1 (Nrp-1) specifically in Tregs leads to enhanced immunity to many transplantable tumors." (PMID 33968014, 2021). "NRP1 is found to be abnormally expressed in many cancers, including GC, breast cancer, and esophageal cancer, and its abnormally expression indicates poor prognosis and cancer metastasis 10-13." (PMID 33995640, 2021). "The abnormal expression of NRP1 has been found in various malignant tumors, including chest tumors, abdominal tumors, and nervous system tumors." (PMID 33014187, 2020). "In silico work has predicted that NRP1 can significantly sequester VEGFs in the pathological condition of cancer and in doing so, improve anti-VEGF efficacy (decreased free-VEGF)." (PMID 32879419, 2020). "Stimulation of IDB0076 to cell-surface expressed NRP1 efficiently induced cellular internalization in cancer cells in comparison with parent antibody, bevacizumab." (PMID 32560565, 2020). "NRP1 is involved in the development of cardiovascular system and the pathogenesis of cancer with an important role in angiogenesis." (PMID 33014187, 2020).
cancer (continued). "Expression of NRP-1 on cancer cells is correlated to their increased oncogenic activity, promoting cancer cell survival, inducing angiogenesis and contributing to therapy resistance." (PMID 33266104, 2020). "Further studies are under way to directly investigate the mechanism which IDB0076 suppresses multi-signal pathways dependent on the expression of NRP1 and co-receptors in various cancer cells via NRP1-coupled internalization." (PMID 32560565, 2020). "NRP-1 is expressed by various cells, including immune cells and cancer cells, and acts as a co-receptor for a variety of receptors implicated in cancer-promoting activities." (PMID 33266104, 2020). "Neuropilin 1) is a transmembrane receptor with several functions related to immunity, development, angiogenesis, and cancer." (PMID 32560565, 2020). "The roles of NRP1 in the growth and invasiveness of prostate, colorectal, kidney, lung, breast... human cancers have been confirmed with animal studies showing that exacerbated angiogenesis and a poor prognosis is correlated with NRP1 expression." (PMID 32766254, 2020). "For example, the co-administration of the iRGD peptide elevated the anti-cancer efficacy of gemcitabine in a murine pancreatic cancer model which showed an overexpression of NRP-1." (PMID 32847045, 2020). "NRP1 protein is highly expressed in different cancer types, such as breast, colorectal, myeloid leukemia, glioma, pancreatic, and prostate tumors." (PMID 31898520, 2020). "Various types of NRP1 blockade are considered a promising combination partner for conventional antiangiogenic agents because an anti-NRP1 antibody has additive effects with an anti-VEGF agent against cancer by enhancing the antiangiogenic action." (PMID 32560565, 2020). "The prognostic impact of NRP1 has been described earlier as being either unfavorable 28, 29, 30 or favorable 31 depending on the cancer type." (PMID 31880322, 2020). "Much evidence has confirmed NRP1 is overexpression in a range of human malignant tumors and is also closely related to the degree of malignancy." (PMID 32472711, 2020). "NRP1 TM domain which contributes to the dimerization of the receptor was shown mandatory to trigger Sema3A-dependent cancer cell migration." (PMID 32351895, 2020). "The effect of NRP-1 on cancer progression is often attributed to increased activation of VEGFR2 in response to VEGF." (PMID 33149867, 2020). "We previously studied a plant-type ceramide that regulates Nrp1, with potential as a novel cancer therapeutic agent." (PMID 32102436, 2020). "The interaction of NRP-1 with vascular endothelial growth factor 165 (VEGF165) is an interesting target for novel cancer therapies and several inhibitors of NRP-1/VEGF165 have been proposed as potential drugs such as the heptapeptide A7R." (PMID 32781656, 2020). "The correlation of NRP-1 overexpression and cancers was analyzed using meta-analysis over 15 studies involving a total of 2049 patients." (PMID 32847045, 2020). "NRP1 has been shown to play a critical role in tumorigenesis, cancer invasion and angiogenesis, through the activation of VEGF, PI3K, and AKT pathways." (PMID 31898520, 2020). "Even though NRP1 is still a promising target for combination regimens with conventional cancer treatments including bevacizumab, the overlapping sets of adverse effects have become the main obstacle to the development of NRP1-targeted drugs." (PMID 32560565, 2020). "Additional studies by our group and by others have further demonstrated the broad relevance of NRP1 in promoting signaling cascades that support cancer cell growth and resistance to therapies." (PMID 32784465, 2020). "For stromal score, NRP1 showed the highest positive correlation across all cancer types (r = 0.59), followed by PLXND1 (r = 0.54), NRP2 (r = 0.50), PLXNC1 (r = 0.48) and PLXNA4 (r = 0.28) (p < 0.0001)." (PMID 32640719, 2020).